IL15 (interleukin 15)
Diseases named in the same sentence as IL15 in open-access papers (continued):
Sharing a sentence is not in itself a finding about the gene and the disease.
autoimmune disease (46 papers, 2005 to 2025). A disorder resulting from loss of function or tissue destruction of an organ or multiple organs, arising from humoral or cellular immune responses of the individual to their own tissue constituents. "This cellular arrangement enables keratinocytes to support TRM cell survival and effector function by trans-presenting IL-15, reinforcing their pathogenic role in autoimmune diseases such as vitiligo." (PMID 40791580, 2025). "IL-15 has been well-established as an important cytokine for immune cell homeostasis that also plays pathogenic roles in autoimmune diseases." (PMID 38919611, 2024). "Several observations support the key role of T cells in the pathogenesis of autoimmune disorders associated with elevated IL-15 expression." (PMID 34922462, 2021). "Local up-regulation of IL-15 in certain autoimmune diseases positively associates with disease severity." (PMID 26417430, 2015). "IL-15 has been implicated in the pathogenesis of several autoimmune diseases as well as LGLL." (PMID 35747794, 2022). "However, studies on the pathogenic role of IL-15 in inflammatory and autoimmune diseases indicate that IL-15 can signal independently of IL-15Rα via the IL-15Rβγc dimer." (PMID 34956227, 2021). "IL-15 is also implicated in several inflammatory disorders and autoimmune diseases." (PMID 23028916, 2012). "Furthermore, the current results revealed that participants with higher adherence to the MDP show lower concentrations of IL-15, an immune cytokine implicated in autoimmune diseases that acts as a potent pro-inflammatory mediator inducing the expression of TNFα, IL-1 and INF-γ." (PMID 35624765, 2022). "Another robust pathogenetic link between LGLL and autoimmune diseases lies in the role of Interleukin-15 (IL-15) in both conditions." (PMID 38238319, 2024). "IL-15 influences the formation of innate and adaptive immunity and contributes to the development of various autoimmune disorders." (PMID 39507777, 2024). "Interleukin-15 (IL-15) is a crucial regulatory inflammatory cytokine that is upregulated in autoimmunity disorders." (PMID 38376769, 2024). "Small nucleotide polymorphisms (SNPs) in IL15 and IL15RA have been shown to increase susceptibility to certain autoimmune diseases." (PMID 38405398, 2024). "As in various autoimmune diseases, IL-15/IL-15Rα complexes were found at high levels in B6/lpr-p2x7KO sera." (PMID 36248812, 2022). "Intriguingly, numerous infectious and autoimmune diseases shared the IL15/IL15RA-centric cytokine response, which is in keeping with prior observations." (PMID 35577777, 2022). "A few studies including ours have also reported that IL-15 is more critical than IL-15Rα in the context of antiviral responses, autoimmune disease and antitumor immunity." (PMID 34956227, 2021). "IL-15 contributes to pathogenesis of autoimmune diseases, such as CD through activation of immune responses." (PMID 33585005, 2020). "IL-15 has been described as a responsible driver for chronic inflammation in autoimmune diseases and hematological malignancies." (PMID 32821971, 2020). "Abnormality of IL-15 expression has been detected in patients with autoimmune diseases and lymphoid malignancies." (PMID 27036031, 2016). "The participation of IL-15 in the pathogenesis of autoimmune diseases has been demonstrated by in vitro studies, murine animal models and clinical trials with an anti-human IL-15 antibody (Ab), AMG714." (PMID 27671547, 2016). "In our current work we assessed expression of IL-15Ralpha, IL-15, IL-6 and TNFalpha in RA compared to OA, a rheumatic non autoimmune disease." (PMID 25879761, 2015). "IL-15 and IL-17 are thought to play an important role in the pathogenesis of RA and related autoimmune diseases." (PMID 24366113, 2013). "Nevertheless, our data showing that IL-15 can help Teff escape the suppression by Treg indicate it is advisable to monitor for autoimmune disease development when using IL-15." (PMID 23028916, 2012).
autoimmune disease (continued). "Although the toxicity of IL-15 may be lower than that of IL-2, some studies have shown that IL-15 can induce the production of a large number of proinflammatory cytokines and may also be involved in the progression of autoimmune diseases." (PMID 40625735, 2025). "In addition to sharing some of IL-2’s properties, such as T-cell activation and NK cell proliferation stimulation, IL-15 also affects CD8+ memory cells and NK cell homeostasis, and increased levels of IL-15 have also been observed in autoimmune diseases." (PMID 40136649, 2025). "Notably IL-15 is involved in the development of autoimmune disease by enhancing the activation and maintenance of IL-17 producing T cells." (PMID 38238319, 2024). "IL-15 plays a critical role in the development and maintenance of various immune cells such as T cells, suggesting elevated T cell activation in AA people, potentially contributing to autoimmune diseases." (PMID 39065221, 2024). "More importantly, the presence of anti-γc antibody could rescue MSCs during coculture with IL-2/IL-15 prestimulated NK cells, suggesting that suppression of γc activity on NK cells might be a potential way to treat autoimmune diseases." (PMID 38106519, 2023). "IL-15 trans-presentation can be blocked by targeting the cytokine receptor subunit IL-2/IL-15Rβ, and this is achieved through the use of Hu-Mik-β1 monoclonal antibody which is used now in clinical trials for treating those with autoimmune diseases." (PMID 37206670, 2023). "Importantly related to development of autoimmune disease, IL-15 enhances activation and maintenance of IL-17 producing T Cells." (PMID 35747794, 2022). "Based on this fact, the current vaccine candidate could be more effective than the one based on biologically active mhIL-15 for treating autoimmune disorders involving an uncontrolled overproduction of IL-15." (PMID 34922462, 2021). "Therefore, this work was aimed to assess the immunogenicity in African green monkeys (AGM) of the vaccine candidate based on IL-15 D8SQ108S, as a potential strategy for treating autoimmune disorders involving IL-15 overexpression." (PMID 34922462, 2021). "IL-15 is a multifunctional cytokine with a documented relationship with autoimmune diseases." (PMID 34281739, 2021). "IL-15 was also reportedly produced by EC under the conditions of viral or autoimmune disease." (PMID 33936069, 2021). "Moreover, active peptides in autoimmune diseases such as [K6T]P8, a peptide able to inhibit the receptor of IL-15, and Cyclotide [T20K]kalata B1, an active peptide in multiple sclerosis able to block immune-competent cells proliferation, were described." (PMID 30208640, 2018). "It has been proposed that an IL-15 antagonist could be useful for treating some autoimmune diseases in which IL-15 acts as proinflammatory cytokine." (PMID 27671547, 2016). "Based on these findings, Y-320 that targets IL-15 and IL-17 could provide a new useful therapy for RA and related autoimmune diseases." (PMID 24366113, 2013). "Deficiency of IL-15 leads to a profound depletion of NK cells, NKT cells, intestinal intraepithelial lymphocytes and CD8+ memory T cells, whereas deficiency of IL-2 leads to lymphoproliferative and autoimmune disease." (PMID 21408124, 2011). "However, chronic infection can result in prolonged and/or heightened IL-15 expression which in turn, at unusual convergence of events, might link infection to development of autoimmune diseases." (PMID 23028916, 2012). "Given the ability of IL-15 to stimulate bystander activation of CD8+ T cells, targeting this cytokine is being considered in organ transplant recipients and in those with autoimmune disease." (PMID 40048261, 2025). "Currently, IL-15 antagonizing antibodies (e.g., AMG 714) have demonstrated efficacy in treating autoimmune diseases such as celiac disease and ankylosing spondylitis, supporting their potential application in vitiligo." (PMID 40791580, 2025).
autoimmune disease (continued). "IL-15 is a proinflammatory cytokine that plays a central role in the pathogenesis of both LGLL as well as of several autoimmune diseases." (PMID 38238319, 2024). "In autoimmune diseases, however, IL-15 appears to be induced in the absence of infection, and it is not clear what signals drive this upregulation." (PMID 38405398, 2024). "Indeed, IL-15 can be produced by macrophage/monocytes, activated NK cells, CD4+ T cells, and B cells, and involved in the pathogenesis of SLE and other autoimmune diseases." (PMID 27412348, 2016). "In addition, disruptions in negative control mechanisms regulating IL-15 expression result in increased IL-15 production, which may predispose to excessive autoreactive T-cell survival and abnormal lymphocyte activation, leading to the development of chronic inflammatory or autoimmune diseases." (PMID 38790942, 2024).
glioblastoma (46 papers, 2015 to 2025). The most malignant astrocytic tumor (WHO grade IV). "In glioblastoma, constitutive IL-15 expression enhanced CAR-T cell proliferation and tumor clearance in an orthotopic xenograft model, supporting the translational feasibility of this approach." (PMID 40771804, 2025). "A recent study revealed that NK cells modified to express IL-21 maintained their anti-tumor activity against glioblastoma over time, whereas IL-15 armored NK cells were more prone to exhaustion after multiple tumor re-challenges." (PMID 40176196, 2025). "IL-15 can also modulate the tumor microenvironment (TME) when secreted by CAR T cells to decrease myeloid-derived suppressor cells (MDSCs) in a glioblastoma (GBM) model." (PMID 39199630, 2024). "When compared with NK-EVs, NK-EVsIL-15 inhibited the growth of glioblastoma xenograft cells in mice significantly, which is the reason why we used IL-15 to stimulate NK cells." (PMID 38258094, 2024). "GD2-specific CAR T cells were modified to release IL-15 to improve the destruction of lung cancer and glioblastoma." (PMID 38693513, 2024). "Recently, IL-15-secreting CAR T cells have been investigated to target MDSC in glioblastoma, making CAR T cells more beneficial." (PMID 38693513, 2024). "NK‐Exo containing IL‐15 (NK‐Exo‐IL‐15) demonstrated greater cytolytic activity against glioblastoma and significantly increased NK cell cytotoxicity." (PMID 37170647, 2023). "Similar results have been seen when designing CAR T-cells to secrete IL-15 within CAR T-cells targeting the glioblastoma antigens fibroblast growth factor-inducible 14 (Fn14) and GD2." (PMID 38136398, 2023). "That is why IL-21, along with IL-2, IL-15 and mesothelin peptides, have been employed to evaluate humoral response using blood samples from patients with glioblastoma." (PMID 37759505, 2023). "We have observed that HODHBt improved NK cell-mediated killing of several cancer cell lines representative of erythroblastoma, ovarian cancer, and glioblastoma compared to treatment with IL-15 alone." (PMID 35867565, 2022). "Several studies highlighted NK cell ability to recognize and kill poorly differentiated tumors and that cytokine-activated (IL2 and/or IL15-activated) NK cells were effective against human breast, colon, melanoma and glioblastoma CSCs." (PMID 33806296, 2021). "Glioblastoma, one of the most aggressive primary brain tumors, has shown antigen loss in mice after treatment with anti-IL13Rα2-CAR.IL15 T cells due to downregulated IL13Rα2 expression." (PMID 34831068, 2021). "The remaining question is if IL-15 is the best cytokine to improve the efficacy of glioblastoma-targeted CAR T cells." (PMID 30863720, 2019). "Examples of Ovs associated with CAR-T cells are given by Ovs expressing IL-15/il-15Rα, potentiating the antitumor effect of EGFR-CAR-NK cells in GBM mouse models, or Ovs expressing IL-7, improving the efficacy of B7H3-CAR-T cells for glioblastoma therapy." (PMID 39199683, 2024). "Additionally, cytokines like interleukin-15 (IL-15) can enhance the antitumor potency of NK cell derived EVs against cancers such as thyroid or breast, and glioblastoma." (PMID 39724442, 2024). "Notably, IL-15 cytokine priming significantly enhanced the anti-tumor efficacy of NK-EVs for glioblastoma treatment." (PMID 37484408, 2023). "NK‐Exo‐IL‐15 inhibited the proliferation of mouse glioblastoma xenografts compared to NK‐Exo." (PMID 37170647, 2023). "NK-EVs by IL-15 priming showed a tumor-homing ability in glioblastoma." (PMID 36068970, 2022). "Previous study reported that NK-EV by IL-15 priming enhanced anti-tumor potency in glioblastoma." (PMID 36068970, 2022). "In regards to high grade glioma, IL-15 has been tested in a xenograft model of glioblastoma." (PMID 30863720, 2019).
glioblastoma (continued). "In addition, we have previously reported a cytokine cocktail, consisting of IL-2, IL-15 and IL-21, that leads to the accumulation of central memory tumor infiltrating T-cells (TILs), obtained from patients with glioblastoma as well as pancreatic tumors." (PMID 29854291, 2018). "Another study found that CAR T-cells modified to fuse IL-15 to the scFv portion of the CAR could deplete immunosuppressive MDSCs in murine glioblastoma models, based on the observation that MDSCs in these models as well as human glioblastoma samples express the α subunit of the IL-15 receptor." (PMID 41019052, 2025). "NKEVs collected from IL-15-primed NK cells had increased concentration of cytotoxic effectors, improved cytolytic activity against cancer cells of glioblastoma, breast cancer, and thyroid cancer, showed improved tumor affinity, and inhibited glioblastoma growth in xenograft mice." (PMID 35874677, 2022). "It has been reported that glioblastoma (GBM) CSCs are vulnerable to IL-2/IL-15-activated NK cells due to their expression of cytotoxicity receptors and ligands (i.e., PVR and Nectin-2) and the reduction of MHC-I molecules on their surface." (PMID 33530455, 2021). "Concerning the positive effect of IL-15 on NK cell persistence, tumor infiltration, and functionality, a herpes simplex-1-based oncolytic virus expressing IL-15/IL-15Rα has resulted in highly significant anti-glioblastoma effects in combination with EGFR CAR NK cells." (PMID 34943898, 2021). "In solid tumors that express disialoganglioside GD2, such as glioblastoma, neuroblastoma, and lung cancer, T cells co-expressing GD2-specific CAR and IL-15 have demonstrated promising preclinical efficacy." (PMID 40771804, 2025). "In this study, CAR-T cells were engineered to secrete both IL-15 and CCL19, and their efficacy was evaluated in a human glioblastoma orthotopic xenograft model." (PMID 40177238, 2025). "For instance, anti-EFGR CAR-NK cells synergized with oncolytic virus expressing IL-15/IL15Rα sushi domain fusion protein enhanced the persistence and infiltration of CAR-NK cells and suppressed the growth of glioblastoma in vitro and in vivo." (PMID 38726000, 2024). "One study has developed a modified CAR T cells with IL15, targeting the receptor IL15 receptor alpha (IL15Rα) expressed on MDSC in human and murine glioblastomas (GBMs)." (PMID 37006306, 2023). "The combination of IL-15 and adoptive cell transfer has shown remarkable outcomes in treating B-cell lymphoma, AML, neuroblastoma, and glioblastoma." (PMID 35806311, 2022). "IL-15 secreting CAR T cells showed enhanced intracranial persistence with resultant tumor regression in the U373 human glioblastoma orthotopic xenograft mouse GBM model." (PMID 34421912, 2021). "In glioblastoma studies, CAR T cells targeting IL-13Rα2 were modified to over-express transgenic IL-15 and demonstrated that IL-15 cytokine secretion was T cell activation dependent and resulted in improved CAR T cell persistence in vitro." (PMID 30863720, 2019). "TIL were expanded from primary (P) or metastatic lesions (ML) in medium containing IL-2, IL-15 and IL-21 from 2 patients with pancreatic cancer (PDAC), 1 patient with glioblastoma (GB), 1 patient with fibrosarcoma (FS) and 1 patient with uveal melanoma (UVM)." (PMID 30400835, 2018). "In the work of Zhenjiang and colleagues, the peripheral blood of patients with glioblastoma was analyzed (glioblastoma = 145; non-glioblastoma = 60) to measure the circulating T cells in the absence or presence of serum cytokines such as IL-2/IL-15/IL-21." (PMID 37759505, 2023). "Moreover, HODHBt enhanced the ability of IL-15-activated NK cells to kill HIV-infected CD4 T cells and different tumor cell lines, including chronic myelogenous leukemia, ovarian carcinoma, and glioblastoma cell lines." (PMID 35867565, 2022).
glioblastoma (continued). "Furthermore, IL-15 has also been integrated with other CARs for targeting different types of tumors, such as IL13Ra-CAR and Fn14-CAR for glioblastoma, GD2-CAR for neuroblastoma, as well as Glypican-3 (GP3) CAR for hepatocellular carcinoma." (PMID 35806311, 2022). "Using in vitro and in vivo migration assays, we found iNSC‐secreted RANTES/IL‐15 increased CAR‐T‐cell migration sixfold and expansion threefold, resulting in greater antitumor activity in a glioblastoma (GBM) tumor model." (PMID 38023712, 2023). "The researchers engineered a fusion protein combining IL-15 and IL-15Rα (designated OV-IL15C), which was expressed within gliomas and demonstrated the ability to enhance cytotoxicity against glioblastoma (GBM) both in vivo and in vitro, while also improving the survival of NK and CD8+ T cells." (PMID 39055561, 2024). "produced OV-IL15C, a herpes simplex 1-based human IL15/IL15Rα sushi domain fusion protein, as well as commercial EGFR-CAR NK cells, and examined their efficiency as a monotherapy and in combination in vitro and several glioblastoma (GBM) mice models." (PMID 36703982, 2022).